RN7SL778P (RNA, 7SL, cytoplasmic 778, pseudogene)
Gene: Miscellaneous RNA gene on chromosome 11 (130,310,180 to 130,310,476, forward strand). Ensembl gene ENSG00000272412.
Homologues: Orthologues: chimpanzee Metazoa_SRP (99% identical), macaque Metazoa_SRP (88% identical). Paralogues in human: RN7SL2 (86% identical), RN7SL1 (86% identical), RN7SL3 (85% identical), RN7SL45P (84% identical), RN7SL15P (82% identical), RN7SL186P (82% identical), RN7SL220P (82% identical), RN7SL680P (82% identical), RN7SL126P (81% identical), RN7SL386P (81% identical), RN7SL127P (81% identical), RN7SL230P (81% identical), and 704 more.